LRRK2 (leucine rich repeat kinase 2)
Diseases named in the same sentence as LRRK2 in open-access papers (continued):
Sharing a sentence is not in itself a finding about the gene and the disease.
cancer (continued). "LRRK2-G2019S carriers have increased cancer risks, particularly brain, breast, colon and blood cancers." (PMID 35247252, 2022). "The opposing effects of LRRK2 and estrogen on PD and cancer development highlight the potential utility of estrogen replacement to slow PD progression and severity, as well as cancer development in PD patients." (PMID 35247252, 2022). "While further analysis is required to determine the contribution of gender and estrogen effects on the increased cancer risks in LRRK2-PD patients, our findings suggest the potential utility of hormonal therapy as a dual preventive measure for PD and cancer." (PMID 35247252, 2022). "Second, we provided a concise account of cancer risks in specific PD populations, comparing between male and female patients and between LRRK2-PD and idiopathic PD patients." (PMID 35247252, 2022). "Here, we found that LRRK2 is required for the interaction of RAD51 and BRCA2, which is responsible for the recruitment of RAD51 to DNA damage sites in LRRK2–high‐expression cancer cells." (PMID 33784003, 2021). "If an oncogenic role of LRRK2 is confirmed, those drugs are of potential use in the field of cancer-targeted therapy as well." (PMID 32722212, 2020). "As such the role of LRRK2 in cancer remains controversial, but serves to further the idea that LRRK2 is involved in more processes than are suggested by its links to PD alone." (PMID 31864390, 2019). "For example, mutations in LRRK2 have been associated with PD, and DAPK1 has been associated with cancer." (PMID 30562929, 2018). "Genetic studies provide additional understanding, since many familial PD genes have been associated with cancer, such as parkin (PARK2), PINK1 (PARK6), DJ-1 (PARK7), and LRRK2 (PARK8)." (PMID 27375474, 2016). "Here we report that LRRK2-IN-1 demonstrates potent anti-cancer activity including inhibition of cancer cell proliferation, migration, and invasion as well as induction of apoptosis and cell cycle arrest." (PMID 24885928, 2014). "In the future, it would be interesting to investigate LRRK2 activity and phosphorylation during different stages of the cell cycle, especially since there are multiple lines of evidence linking LRRK2 to cancer." (PMID 22952710, 2012). "On the other hand, findings from Ruiz-Martinez and collaborators reported no clear association between the R1441G or G2019S LRRK2 variant and any specific cancer type." (PMID 41300754, 2025). "Notably, studies utilizing outlier analysis have identified TM4SF4 and LRRK2 as key oncogenic drivers, demonstrating that transcriptomic profiling can aid in discovering novel targets for personalized cancer therapy." (PMID 40872585, 2025). "Research on ROCO proteins significantly intensified since the identification of links between ROCO proteins and human disease, notably, leucine-rich repeat kinase 2 (LRRK2) with Parkinson’s disease (PD) and death-associated protein kinase 1 (DAPK1) with cancer (Marín, 2006; Terheyden, 2018)." (PMID 39246816, 2024). "The scope of the studies includes model experiments, an introduction or a correction of disease-associated mutations, the analysis of the function of individual genes (e.g., USP18 and LRRK2 and the generation of transgenic macrophages and myeloid cell lines for cancer therapy." (PMID 37629049, 2023). "Functional studies in experimental models to elucidate the pathophysiology of PD and cancer contributed by kinase functions and targets of LRRK2 in the cell cycle may facilitate identification of therapeutic targets." (PMID 35247252, 2022).
cancer (continued). "These expression patterns mirror our findings of increased brain, breast, colon, and hematological cancers, further strengthening the association between LRRK2 and cancer and increasing the value of targeting LRRK2 for therapeutic treatment of both PD and cancer." (PMID 35247252, 2022). "These clinical and experimental observations provide support linking LRRK2 to cancer." (PMID 35247252, 2022). "Emerging evidence suggests that LRRK2 mutations are highly related with cancers such as colon cancer and nonskin cancer." (PMID 33784003, 2021). "It has been claimed that LRRK2 PD cases have higher prevalence of cancer compared to sporadic PD." (PMID 33584195, 2021). "Interestingly, there is previous evidence of inhibitory activity against LRRK2 for one of the top candidates: The anti-cancer drug Sunitinib is a receptor tyrosine kinase inhibitor that has been shown to efficiently inhibit LRRK2." (PMID 34285770, 2021). "Recently, the role of LRRK2 in cancer has received considerable attention." (PMID 33784003, 2021). "Previous studies have linked LRRK2 and LRRK2 kinase activity to DRP1 activation via phosphorylation at several sites including T595 in neurons and S616 in a neuron-like carcinoma cell line." (PMID 32057291, 2020). "The silencing of lipoxygenase (ALOXE3) and and inhibitor of peroxidase (LRRK2) may contribute to elevated pro-cancer COX-mediated peroxidase activity." (PMID 30253781, 2018). "It is interesting to note that LRRK2 is also involved in cancer signalling pathways." (PMID 25899482, 2015). "This may support the existence of different functions for LRRK2 in PD, cancer and immune disorders, and it suggests caution in extrapolating general information from different model systems and from experiments involving the use of mutant LRRK2." (PMID 25899482, 2015). "Whether a kinase inhibitor of LRRK2 would have any impact on cancer is very difficult to predict, but might be considered a potential extra target for drug development." (PMID 22361010, 2012). "Finally, as a result of their putative kinase function, PINK1 and LRRK2 are attractive potential targets in the treatment of PD and cancer even though their potential influence in tumour growth remains mostly indirect and suggestive thus far." (PMID 21203498, 2010). "No cases of cancer were reported in the dual LRRK2/GBA1 mutation carriers." (PMID 41300754, 2025). "There were no other associations between specific cancer types and the LRRK2 mutation." (PMID 33584195, 2021). "Some genes, such as LRRK2 and PRKN, may be associated with both cancer and PD." (PMID 32733355, 2020). "The hypothesized role of an increase in kinase activity of LRRK2 in cancer development, if confirmed via in vitro studies, potentially paves the way for the use of small molecule LRRK2 inhibitors beyond PD: LRRK2-amplificated cases are putative candidates for such treatment." (PMID 32722212, 2020). "No other associations between harboring a LRRK2 mutation and specific cancers types were uncovered." (PMID 29568677, 2018). "No other associations between harboring a LRRK2 mutation and specific cancer types were uncovered." (PMID 29568677, 2018). "In total, 12 LRRK2 PD− had cancer and 4 LRRK2 PD+ had cancer before PD, indicating that cancer in association with the LRRK2 mutation may not be limited to the presence of PD." (PMID 29568677, 2018). "It is unknown if manifesting LRRK2 mutation carriers more or less vulnerable to cancer than never‐manifesting mutation carriers." (PMID 29568677, 2018). "Taken together, our findings identify USP7 as a novel deubiquitinating enzyme of LRRK2 that positively regulates its stability and plays an oncogenic role in AML, with implications for AML cancer progression and potential therapeutic targets." (PMID 40907896, 2025). "This provides rationale for inhibiting LRRK2 to suppress HR in combination with PARP, thereby inducing synthetic lethality in cancer cells overexpressing LRRK2." (PMID 33784003, 2021).
cancer (continued). "Certain kinase inhibitors have been found to inhibit DCLK1 kinase activity, such as that of LRRK2-In-1, XMD-892 and DCLK1-IN-1; however, they are in the process of preclinical trials for cancer treatment." (PMID 33762936, 2021). "The specificity of LRRK2-IN-1 for DCLK1 and the results of our studies support the development of DCLK1 kinase inhibitors against cancer." (PMID 24885928, 2014). "Additionally, three studies offered that LRRK2, an inhibitor of DCLK1, can prevent DCLK1 kinase activity and has the effect of anti-cancer activity." (PMID 35717205, 2022). "Since it has been shown that LINK-A controls HIF-1α stabilization through interaction with PTK6 and LRRK2 in cancer cells, this prompted us to evaluate whether PTK6 and LRRK2 mediate increased LINK-A–induced HIF-1α expression in RA FLSs." (PMID 34877935, 2021). "Genetic alterations of leucine-rich repeat kinase 2 (LRRK2), one of the most important contributors to familial Parkinson’s disease (PD), have been hypothesized to play a role in cancer development due to demographical and preclinical data." (PMID 32722212, 2020). "Many of these genes, including KEAP1, HNF1A, NFE2L2 and LRRK2, have implied roles in cancer but no strong mechanistic links to date (Discussion)." (PMID 30803482, 2019). "Our analysis indeed shows that LRRK2 amplification, given its negative prognostic significance, could play a role in cancer development and may be clinically actionable." (PMID 32722212, 2020). "Thus, our study reveals a novel role for pathogenic LRRK2 related to proper centrosome functioning, which may not only contribute to neurodegeneration, but may also account for some early manifestations of the disease and the increased incidence of cancer seen in PD patients." (PMID 29357897, 2018). "The remaining genes are a part of several pathways involved in cancer etiology such as: Negative regulation of stress activated MAPK cascade (PBK and PINK1), intracellular signal transduction and regulation of autophagosome assembly (LRRK2 and PINK1) and RNA degradation (PABC3 and DDX6)." (PMID 29879995, 2018). "The LRRK2 kinase, also known as PARK8, is not considered to be a classical cancer gene." (PMID 20053295, 2010).
infection (49 papers, 2013 to 2025). The state of being infected such as from the introduction of a foreign agent such as serum, vaccine, antigenic substance or organism. "To understand how Lrrk2 G2019S mutation affects the immunophenotype of the colonic lamina propria at baseline and during infection, we completed scRNAseq." (PMID 40883285, 2025). "To further explore the impact of the G2019S mutation in LRRK2 during C. rodentium infection, we evaluated the overall response of these mice in early infection." (PMID 40883285, 2025). "In different models, the LRRK2 substrate Rab10 has been implicated in immune functions related to both infection and PD." (PMID 38862989, 2024). "Overexpression of both NOD2 WT and NOD2 R702W proteins increased the ROS production in all three LRRK2 variant cell lines upon infection with BCG." (PMID 36972292, 2023). "LRRK2 knockout mice have an altered gut microbiota, leading to an impaired defense against infection and an increased risk of infection." (PMID 33255983, 2020). "Surprisingly, the infection of G2019S LRRK2 mice with reovirus causing invasion of the nervous system led to greater mortality from encephalitis in females." (PMID 33291304, 2020). "In different models of infection, LRRK2 has been implicated in the regulation of type I interferon (IFN) production." (PMID 32643832, 2020). "Impaired clearance of S. typhimurium was also observed in vivo using LRRK2 knockout mice, which were more markedly more susceptible to infection and unable to mount a sufficient inflammasome response." (PMID 32210756, 2020). "A 2009 New England Journal of Medicine study found that SNPs in LRRK2 are associated with susceptibility to infection with M. leprae." (PMID 31192157, 2019). "In vivo, LRRK2 deficiency in mice resulted in a significant decrease in M. tuberculosis burdens early during the infection." (PMID 29789389, 2018). "Regarding LRRK2, SNPs in this gene are associated with the multibacillary form of human infection with Mycobacterium leprae, another intracellular pathogen." (PMID 30374342, 2018). "Our ongoing studies for the role of PD-associated genes in the immune system [foremost LRRK2] prompted us to establish this experimental paradigm to model a natural route of infection." (PMID 28477284, 2017). "To assess how the Lrrk2 G2019S mutation may alter cell-cell communication during infection, we performed CellChat analysis comparing WT and Lrrk2 G2019S mice." (PMID 40883285, 2025). "Based on the current literature, scientists speculate that an overactivated LRRK2 kinase may be beneficial during early life, protecting mutation carriers against infections." (PMID 38835904, 2022). "Similarly, LRRK2-deficient mice show increased bacterial colonization and reduced survival after infection with Salmonella typhimurium." (PMID 38835904, 2022). "It would also be beneficial to understand whether the kinase activity of LRRK2 during the infection is associated with Rab32 and plays a pivotal role in the defense mechanism of the host against Salmonella." (PMID 33426511, 2021). "Intriguingly, mice with the G2019S LRRK2 mutation showed improved bacterial control of S. typhimurium, adding to suggestions that some LRRK2 mutations may constitute an evolutionary advantage against infection." (PMID 32210756, 2020). "Our present results suggest that LRRK2 may play novel roles in both the innate immune system and the pathogenesis of various diseases such as intracellular pathogenic infection." (PMID 32164260, 2020). "The protective effects of LRRK2 during bacterial infections seem to be mediated by its kinase activity since knockin mice expressing the G2019S variant were able to better control the infection, in contrast to mice expressing the kinase dead variant D1994S." (PMID 32410948, 2020).
infection (continued). "Furthermore, paneth cells from Lrrk2-KO mice are more susceptible to infection from Listeria monocytogenes, with a loss of Lrrk2 decreasing lysozyme levels, an antimicrobial enzyme responsible for the degradation and lysis of bacteria." (PMID 32508566, 2020). "LRRK2 mutation and the alteration of expression level induced by infection and peripheral inflammation may affect the activation and function of DC and microglia in neurodegenerative disorders, such as PD." (PMID 32164260, 2020). "Therefore, we sought to understand how LRRK2 deficiency influences Mtb pathogenesis in macrophages ex vivo and during an in vivo infection." (PMID 32057291, 2020). "LRRK2 kinase activity is positively linked to a pro-inflammatory response and might thus be beneficial to control peripheral pathogen infections." (PMID 32410948, 2020). "Importantly, we found that the loss of LRRK2 enhances early innate immune responses to Mtb in vivo with potential consequences in the cross talk of innate and adaptive immunity later during the infection." (PMID 29789389, 2018). "The blocking of autophagy by EBV at the first infection stage causes the inactivation of LRRK2." (PMID 30133498, 2018). "Thus, in accordance with the ‘second hit hypothesis’ in PD, the number and severity of infections that an LRRK2 mutation carrier has to endure may define the penetrance of the movement disorder in this individual." (PMID 38835904, 2022). "However, it is important consider that a complete abolition of LRRK2 kinase activity in the peripheral immune system may have deleterious effects, with increased risk of infection and decreased pathogen control, as suggested by data from Lrrk2-KO models." (PMID 32508566, 2020). "However, given that loss of LRRK2 may lead to higher risks of infection and inflammation in peripheral blood cells, therapeutic windows will have to be carefully monitored to avoid unwanted effects on the immune system." (PMID 32293561, 2020). "Collectively, these data suggest that LRRK2 has a diverse functional role in many organs outside of the CNS, and is required for the healthy function of organs such as the lung and kidneys, and may be associated with efficient host responses to infections." (PMID 32508566, 2020). "Because LRRK2 inhibitors are a major area of drug development for the treatment of PD, it is crucial to understand how both loss of and mutations in this protein might impact the ability of patients receiving such therapies to respond to and clear infection." (PMID 32057291, 2020). "Genome-wide association studies link leucine rich repeat kinase 2 (LRRK2) variants, related to one of the leading heritable forms of PD, to higher susceptibility to the autoimmune Crohn’s disease and Mycobacterium leprae infection, reinforcing a strong link between elevated risk of infection and PD." (PMID 31481676, 2019). "This work reveals that endogenous LRRK2 G2019S impacts the very early response to infection in the gut, and that amongst all cells of the lamina propria, neutrophils are arguably the most prominently affected by the mutation in this setting." (PMID 40883285, 2025). "Together, these results suggest that Lrrk2 G2019S mice undergo a more severe inflammatory process in the colon tissue compared to WT mice during infection." (PMID 40883285, 2025). "Numerous investigations have highlighted the role of LRRK2 in relation to infection, especially in response to bacterial pathogens." (PMID 40867920, 2025). "LRRK2 is widely expressed in the immune system and its kinase activity confers a survival advantage against infection in animal models." (PMID 39062657, 2024). "Consistent with a previous report, relative to LRRK2 WT expressing cells, the production of ROS was significantly lower in LRRK2 KO cells in response to infection (P < 0.01 at 1h p.i., P < 0.001 at 2-6h p.i.)." (PMID 36972292, 2023). "We next looked at gene expression differences in Lrrk2 KO vs. HET BMDMs at 4 hr post-infection with Mtb." (PMID 32057291, 2020).